ERBB2 (erb-b2 receptor tyrosine kinase 2)
Diseases named in the same sentence as ERBB2 in open-access papers (continued):
Sharing a sentence is not in itself a finding about the gene and the disease.
acute leukemia (2 papers, 2015 to 2020). A clonal (malignant) hematopoietic disorder with an acute onset, affecting the bone marrow and the peripheral blood. "Despite the paucity of ERBB2 expression in hematopoietic tissues, in this study, we discovered three oncogenic ERBB2 point mutations—R188C, P489L, and L1157R—in patients with acute leukemia." (PMID 32366937, 2020).
alcoholic steatohepatitis (2 papers, 2021 to 2023). "The strongest association of ErbB2-positive cases was observed with diagnosis of alcoholic steatohepatitis (ASH)." (PMID 32591879, 2021). "We found a cytoplasmic and nuclear ErbB2 expression in hepatocytes from different disease conditions with the strongest expression detected in alcoholic steatohepatitis." (PMID 32591879, 2021). "Most frequently, we detected ErbB2 expression in alcoholic steatohepatitis (ASH)." (PMID 32591879, 2021).
autoimmune hepatitis (2 papers, 2021 to 2023). Hepatitis caused by autoantibodies. "Regenerative and proliferative activity of hepatocytes in viral or autoimmune hepatitis was much higher than in ASH but those cases almost always were ErbB2 negative." (PMID 32591879, 2021). "In other hepatitides, i.e., viral hepatitis, autoimmune hepatitis, drug-induced hepatitis, or graft-versus-host disease, ErbB2 immunoreactivity of liver tissue was negative in most cases independent of inflammatory activity." (PMID 32591879, 2021).
cholestasis (2 papers, 2020 to 2021). Impairment of the bile flow caused by obstruction within the liver, or outside the liver in the bile duct system. "Nuclear ErbB2 positivity significantly correlated with histologic parameters of hepatocellular damage including inflammatory activity in steatohepatitis, hepatocellular ballooning, and cholestasis." (PMID 32591879, 2021).
Cirrhosis (2 papers, 2021). A chronic disorder of the liver in which liver tissue becomes scarred and is partially replaced by regenerative nodules and fibrotic tissue resulting in loss of liver function. "ErbB2 expression in cirrhosis often was confined to the hepatocellular layers in the periphery of the cirrhosis nodules resulting in a gradient of ErbB2 expression within the cirrhosis nodule." (PMID 32591879, 2021).
co-infection (2 papers, 2023). "No HPV co-infection was detected by in situ hybridization or PCR-based screenings and no ERBB2 gene amplification was detected by fluorescence in situ hybridization." (PMID 37847488, 2023).
edema (2 papers, 2020 to 2022). An abnormal accumulation of fluid beneath the skin, or in one or more cavities of the body. "One patient who was infused with 1 × 1010 anti-ERBB2 CAR-T suffered several grade 4 adverse events including gastrointestinal bleeding and pulmonary edema." (PMID 35274719, 2022).
gastric cardia adenocarcinoma (2 papers, 2022 to 2023). A carcinoma that arises from glandular epithelial cells of the cardia of stomach. "In gastric cardia adenocarcinoma, focal amplification of ERBB2 is correlated with a better prognosis, whereas focal amplification of EGFR is associated with a worse prognosis." (PMID 37448518, 2023). "Therefore, ecDNA-derived ERBB2 focal amplifications might serve as a favourable prognostic biomarker in gastric cardia adenocarcinoma patients." (PMID 35844796, 2022). "As focal amplification was mainly driven by ecDNA, the detection of ERBB2 and EGFR ecDNAs should be considered as potential prognostic biomarkers in gastric cardia adenocarcinoma." (PMID 37448518, 2023).
glaucoma (2 papers, 2021 to 2023). Increased pressure in the eyeball due to obstruction of the outflow of aqueous humor. "Ephrin, NGF, and ERBB2 as three important pathways identified by their high expression are shared by glaucoma and miR-204 target genes." (PMID 34646884, 2021).
hereditary cancer syndrome (2 papers, 2017 to 2021).
hypertrophic cardiomyopathy (2 papers, 2012 to 2018). A condition in which the myocardium is hypertrophied without an obvious cause. "We propose that this novel model of ErbB2 over-expression in cardiomyocytes meets the criteria for the model of hypertrophic cardiomyopathy (HCM), which is characterized by cardiomyocyte hypertrophy, myocardial disarray and interstitial fibrosis." (PMID 22912742, 2012). "Reduced cardiac output and decreased blood pressure, seen in ErbB2 transgenic mice, are other features often observed in HCM human patients particularly during exercise tests and hypertrophic cardiomyopathy mouse models." (PMID 22912742, 2012). "Additionally, compared to Hypertrophic Cardiomyopathy mouse models, ErbB2 transgenic mice have a much greater degree of disarray, and thus may be useful in dissecting molecular mechanisms of disarray and the effects of myocardial disarray on cardiomyocyte physiology." (PMID 22912742, 2012).
kidney neoplasm (2 papers, 2021 to 2022). A benign or malignant neoplasm affecting the kidney. "Compared to normal kidney tissues, primary kidney tumors do not have a remarkable ERBB2 gene increase in a profiling gene interactive expression." (PMID 36172165, 2022).
listeria infections (2 papers, 2022). "Therefore, these compounds could be considered for use as a potential treatment for listeriosis by inhibiting proteins such as, IL2, MAPK1, SRC, EGFR, PTPRC, TNF, IL1B, and ERBB2." (PMID 36671206, 2022).
non-alcoholic fatty liver disease (2 papers, 2019 to 2025). "Next we analyzed the correlation between ERBB2 and various clinico‐pathological characteristics, including gender, age (<55 and ≥55 years), TNM stage, risk factors (HBV infection, HCV infection, nonalcoholic fatty liver disease), and alcohol abuse, using the TCGA cohort." (PMID 30714677, 2019).
pancreatitis (2 papers, 2020 to 2022). Inflammation of the pancreas. "The autocrine loop of Nrg-1/2 with ErbB2/ErbB3 heterodimer elucidates the activation of downstream pathways and their crosstalk with one another as a key event in the conversion of normal stem cells into CSCs under inflammatory microenvironments such as pancreatitis." (PMID 35177646, 2022). "As a first step to address this question, we characterized the ERBB2 expression pattern in wild-type (WT) mice and in mice expressing oncogenic KRASG12D in acinar cells (ElaCER KrasG12D mice), in the absence or in the presence of cerulein-induced pancreatitis." (PMID 32251323, 2020).
primary sclerosing cholangitis (2 papers, 2015 to 2021). "High expression and activation of ERBB2 have been found in biliary lithiasis and primary sclerosing cholangitis and have been implicated in pathologic proliferation of cholangiocytes." (PMID 34413880, 2021).
seminoma (2 papers, 2020 to 2024). A radiosensitive malignant germ cell tumor found in the testis (especially undescended), and extragonadal sites (anterior mediastinum and pineal gland). "Similar pathways were present in non-seminomas as well, with miRNAs and mRNA fragments showing cancer related pathways, with mTOR, MAPK, ERBb2, and PI3K-Akt showing highest significance." (PMID 33251139, 2020).
serous cystadenoma (2 papers, 2018 to 2019). A serous neoplasm in which the cysts and papillae are lined by a single layer of cells without atypia, architectural complexity or invasion. "LGSC characterized by KRAS, BRAF, and ERBB2 gene mutations is thought to show stepwise progression and develop from serous cystadenomas and SBT." (PMID 29321056, 2018). "We aimed to identify genetic variations in KRAS, BRAF, PIK3CA, and ERBB2 in LGSC/SBT/serous cystadenomas (SCAs) in a Japanese population." (PMID 31892193, 2019).
signet ring cell gastric adenocarcinoma (2 papers, 2018 to 2024). A poorly cohesive gastric adenocarcinoma characterized by malignant cells containing intracytoplasmic mucin. "In the meantime, after a neurosurgery consultation, the patient was proposed for a biopsy of the causa equina, which showed metastatic spread of a signet ring cell gastric adenocarcinoma c-erb2/NEU 2+ (antibody c-ErbB2 DAKO); negative fluorescence in situ hybridization (FISH) was utilized." (PMID 38921299, 2024).
acral lentiginous melanoma (1 paper, 2023). A form of melanoma occurring most often on the plantar, palmar, subungual, and periungual skin. "We also found an association of the current study’s miRNA signature with ERBB2 (also known as HER2, neu, and NGL), which is known to be amplified in acral lentiginous melanoma and mucosal melanoma." (PMID 37175874, 2023).
adenocarcinoma of the urinary bladder (1 paper, 2021). "Amplification of the ERBB2 gene was found in one patient (1/1) with adenocarcinoma of the urinary bladder." (PMID 34768978, 2021).
allergic asthma (1 paper, 2024). A asthma with a basis in a pathological type I hypersensitivity reaction. "The current results suggested that CASP3, CCND1, ICAM1, RAF1, and ERBB2 expression are causally related to the risk of allergic asthma." (PMID 39769348, 2024). "The present MR results suggested the presence of associations between the risk of allergic asthma and BAX, CASP3, CCND1, ICAM1, PEBP1, RAF1, and ERBB2 expression." (PMID 39769348, 2024). "Based on the inverse variance weighted method, the MR analysis provided evidence of associations between allergic asthma and BAX, CASP3, CCND1, ERBB2, ICAM1, PEBP1, and RAF1 in the blood." (PMID 39769348, 2024).
ameloblastoma (1 paper, 2022). The most common odontogenic tumor, arising from the epithelial component of the embryonic tooth and usually affecting the molar-ramus region of the mandible or maxilla. "According to the present results, ERBB2 was significantly downregulated in ameloblastoma tissue compared to the corresponding normal area (FC = 0.43, P value = 0.002)." (PMID 36160115, 2022).
aneurysm (1 paper, 2022). Bulging or ballooning in an area of an artery secondary to arterial wall weakening. "Among them, six hub genes might be the core genes for the rupture of aneurysms, including APP, JUN, GSK3B,ErbB2, PPBP and THBS1." (PMID 35432454, 2022).
atopic asthma (1 paper, 2020). An asthma that is characterized by symptoms that are triggered by an allergic reaction caused by inhaled allergens such as dust mite allergen, pet dander, pollen and mold. "Restoration of ErbB2 function may contribute to improve the function of airway epithelial healing, which leads to ameliorate airway inflammation shown in severe asthmatics, especially in atopic asthma patients who have persistent airway epithelial damage by allergic external pathogens." (PMID 33217964, 2020).
autosomal recessive polycystic kidney disease (1 paper, 2022). An inherited disorder characterized by the development of cysts affecting the collecting ducts. "In mouse model of autosomal recessive polycystic kidney disease, it inhibited spectrum of key tyrosine kinases (EGFR, HER2/ErbB2, c-Src) that are associated with cell proliferation and angiogenesis." (PMID 35328738, 2022).
celiac disease (1 paper, 2023). An autoimmune genetic disorder with an unknown pattern of inheritance that primarily affects the digestive tract. "One SB-PCC, which was associated with celiac disease and showed a PCC-NOS histology, harbored a point mutation of the ERBB2 gene." (PMID 36812376, 2023).
cervical disease (1 paper, 2015). "For example, in the case of cervical disease, the expression of other RTKs such as ErbB-2, or enzymes such as cyclooxygenase-2 may impact pathway expression." (PMID 26209091, 2015).
childhood onset asthma (1 paper, 2021). Asthma that starts in childhood. "The TAGC-only colocalization was an meQTL-GWAS pair that was associated with cg10374813 and the three TAGC and childhood onset asthma colocalizations were eQTL-meQTL-GWAS triplets associated with two genes (ORMDL3 and ERBB2) and two CpGs (cg18711369 and cg2270401)." (PMID 34629083, 2021).
Cholestatic liver disease (1 paper, 2021). "Nuclear ErbB2 expression is a diagnostic marker for toxic injury; membranous ErbB2 positivity indicates cholestatic liver disease." (PMID 32591879, 2021). "Cholestatic liver disease was a further entity associated with frequent ErbB2 expression in this study." (PMID 32591879, 2021). "Interestingly, ErbB2 expression pattern was different than described before; in cholestatic liver disease, hepatocytes showed an accentuated membranous ErbB2 expression." (PMID 32591879, 2021).
cholesteatoma (1 paper, 2015). A pathologic process characterized by the proliferation of keratinizing squamous epithelium resulting in the accumulation of keratin and cells in the middle ear and/or mastoid. "Inhibition of ERBB2IP would therefore be expected to disinhibit ERBB2, enhancing the proliferation of epithelial cells and growth of the cholesteatoma, which has been shown to express ERBB2 as well as several EGF family members." (PMID 25922834, 2015).
cleft palate (1 paper, 2021). Cleft palate is a fissure type embryopathy that affects the soft and hard palate to varying degrees. "Overexpression of miR-4680-3p inhibited cell proliferation in a dose-dependent manner through the suppression of expression of ERBB2 and JADE1, which are known cleft palate-related genes." (PMID 33585479, 2021).
Cocaine addiction (1 paper, 2025). "By broadening our perspective to incorporate the KEGG pathways, we also observed that ERBB2 (Hypo), NCK1 (Hypo), and JUN (Hyper) are members of the ErbB signaling pathway, while BDNF (Hyper) and JUN (Hyper) are constituents of the Cocaine addiction pathway." (PMID 40217422, 2025).
colorectal polyp (1 paper, 2022). "Finally, the correlation between the ERBB2 mutational targets and colorectal polyp recurrence is first identified in the NGS cohort and was ulteriorly validated in a multicenter cohort." (PMID 35402217, 2022).
demyelinating disease (1 paper, 2022). A broad group of disorders that affect the myelin sheaths that cover the neurons. "Therapeutic interventions targeted to block kinase activity of ErbB2 may have the potential to prevent nerve degeneration in leprosy and other demyelinating diseases at an early stage before the progression of these neurodegenerative diseases." (PMID 35281455, 2022).
diverticular disease (1 paper, 2019). A complex disorder characterised by mucosal outpouchings (diverticulae) of the colonic wall which can become infected and inflamed leading to diverticulitis, perforation and bleeding. "Further studies are required to unravel whether a deficiency of the NRG1/ErbB2/ErbB3 system observed in DD may also occur in asymptomatic diverticulosis." (PMID 31920561, 2019).
duodenal tumor (1 paper, 2015). "ERBB2 mutations were present in 12% of patients, and significantly associated with duodenal tumor location." (PMID 26676271, 2015).
eccrine carcinoma (1 paper, 2012). An adenocarcinoma with eccrine differentiation arising from the sweat glands. "None of the six apocrine-eccrine carcinomas in our series with (2+) HER2 overexpression demonstrated ERBB2 gene amplification." (PMID 23056620, 2012).
Flavivirus Infections (1 paper, 2020). Infections with viruses of the genus FLAVIVIRUS, family FLAVIVIRIDAE. "Moreover, we showed that Akt and ErbB2 levels decrease during flavivirus infection as a result of NS5-HSP90 interaction, implying that processes mediated by these and other HSP90-client kinases are likely altered during infection, possibly contributing to viral pathogenesis." (PMID 32272626, 2020).
heart tumors (1 paper, 2024).
hydronephrosis (1 paper, 2011). Collection of urine in the renal pelvis that results in dilatation of the renal pelvis and calyces. "Multivariate analysis identified erbB2 and NFκB overexpression and the presence of hydronephrosis as significant and independent risk factors for CRT resistance, with respective relative risks of 11.8 (P = 0.014), 15.4 (P = 0.024) and 14.3 (P = 0.038)." (PMID 22102915, 2011). "Multivariate analysis identified erbB2 and NFκB overexpression and hydronephrosis as significant and independent risk factors for chemoradiation resistance with respective relative risks of 11.8 (P = 0.014), 15.4 (P = 0.024) and 14.3 (P = 0.038)." (PMID 22102915, 2011).
left ventricular hypertrophy (1 paper, 2012). Enlargement of the LEFT VENTRICLE of the heart. "The left ventricle cavity (LVEDD 2.16±0.33 vs. 2.91±0.28 mm) was significantly smaller during diastole in ErbB2 transgenic mice, suggesting concentric left ventricular hypertrophy as shown in representative M-mode." (PMID 22912742, 2012).
leiomyoma (1 paper, 2013). A well-circumscribed benign smooth muscle neoplasm characterized by the presence of spindle cells with cigar-shaped nuclei, interlacing fascicles, and a whorled pattern. "It is also of interest that EGFR was only identified in the leiomyoma to leiomyoma comparison, while ERBB2 was identified only in leiomyoma compared to myometrium." (PMID 23785396, 2013). "According to the IPA analysis, one of the top 5 significant network signaling pathways in leiomyoma compared to myometrium was centered on down-regulation of ERBB2." (PMID 23785396, 2013). "A similar mechanism may be at play in smooth muscle cells of leiomyoma where the decreased or absent gene expression of ERBB2 underlies a defective contractile and differentiation signal." (PMID 23785396, 2013).
malignant mesothelioma (1 paper, 2013). A malignant neoplasm of the pleura or peritoneum, arising from mesothelial cells. "The present study revealed that in contrast to this ErbB2-Herceptin axis, YS110 treatment abundantly augments nuclear localization of CD26, and consequently suppresses POLR2A expression, leading to inhibition of malignant mesothelioma cell growth." (PMID 23638030, 2013).
mucosal melanoma (1 paper, 2025). A melanoma that arises from a mucosal site. "In mucosal melanomas, ERBB2 amplification occurs in 2%-5% of cases and correlates with aggressive behavior and poor prognosis." (PMID 40969261, 2025). "Therefore, routine ERBB2 IHC/FISH and NGS testing is recommended for cervical mucosal melanoma to identify potential beneficiaries." (PMID 40969261, 2025).
myxofibrosarcoma (1 paper, 2025). A malignant fibroblastic neoplasm arising from the soft tissue. "In one patient with metastatic low-grade myxofibrosarcoma and ERBB2 amplification along with positive HER2/neu immunohistochemistry, a targeted therapy with trastuzumab + pertuzumab was performed as a fifth-line treatment following heart transplantation." (PMID 40571919, 2025).
osteomyelitis (1 paper, 2020). An acute or chronic inflammation of the bone and its structures due to infection with pyogenic bacteria. "It is somewhat unexpected that the up-regulated expression of TWIST1 and NANOG was only found in the cells from bone marrow but not in those from blood and the expression of ERBB2 was only down-regulated in the cells from blood in implant-associated osteomyelitis mice models." (PMID 32595631, 2020). "Therefore, up-regulation of TWIST1 and NANOG and down-regulation of ERBB2 might indicate activation of immune cells in response to S. aureus osteomyelitis." (PMID 32595631, 2020). "ERBB2, TWIST1, and NANOG were screened out as the most valuable osteomyelitis-related genes (OMRGs)." (PMID 32595631, 2020).